PTAFR (platelet activating factor receptor)
Diseases named in the same sentence as PTAFR in open-access papers (continued):
Sharing a sentence is not in itself a finding about the gene and the disease.
liver cancer (1 paper, 2023). An epithelial or non-epithelial malignant neoplasm that arises from the liver. "Thus, PAIP1 would positively regulated PTAFR and IL1R2 in both HepG2 cells and liver cancer tissues." (PMID 37101794, 2023). "Thus, more work could be conducted to explore the roles of PTAFR and IL1R2 in liver cancer." (PMID 37101794, 2023).
myocardial ischemia (1 paper, 2021). A disorder of cardiac function caused by insufficient blood flow to the muscle tissue of the heart. "Platelet activating factor receptor (PAFR) plays a key role in myocardial ischemia reperfusion (MIR) injury." (PMID 34104104, 2021).
nasal polyps (1 paper, 2024). "On the other hand, the upregulation of PTAFR gene expression in nasal polyps from both nonECRS and ECRS suggests that PTAFR upregulation, enhancing the possibility of PAF-signaling upregulation, is associated with the formation and/or maintenance of nasal polyps." (PMID 38396790, 2024). "In summary, this study’s examination of PTAFR gene expression in nasal polyps reveals that severe type 2 inflammation leads to a particularly high PAF metabolism in nasal polyps, which may induce the proliferation and maintenance of nasal polyps." (PMID 38396790, 2024).
oligodendroglioma (1 paper, 2018). A well-differentiated (WHO grade II), diffusely infiltrating neuroglial tumor, typically located in the cerebral hemispheres. "Many of these candidates (e.g. ELTD1, SDHB, SEPW1, SLC17A7, SZRD1, THAP3, ZBTB17) are likely to push, whereas others (e.g. CAP1, HBXIP, KLK6, PARK7, PTAFR) might counteract oligodendroglioma development." (PMID 29890994, 2018). "Interestingly, several of these genes (e.g. ELTD1, SDHB, SEPW1, SLC17A7, SZRD1, THAP3, ZBTB17) are likely to push, whereas other genes (e.g. CAP1, HBXIP, KLK6, PARK7, PTAFR) might restrict oligodendroglioma development." (PMID 29890994, 2018).
periodontitis (1 paper, 2024). An acute or chronic inflammatory process that affects the tissues that surround and support the teeth. "Specifically, we observed that IL-1β, SRGN, CXCR1, and PTAFR exhibited significant upregulation at both the RNA transcript and protein translation levels in periodontitis patients compared to healthy periodontal patients." (PMID 38491529, 2024). "The analysis revealed simultaneous significant upregulation of IL1β, SRGN, CXCR1, FGR, ARHGEF2, and PTAFR in all six periodontitis-related datasets." (PMID 38491529, 2024). "Similar to the mRNA expression results, enhanced protein expression of IL1β, SRGN, CXCR1, and PTAFR was observed in the periodontitis group." (PMID 38491529, 2024). "Additionally, we conducted immunohistochemical analysis to explore the protein translation of IL1β, SRGN, CXCR1, and PTAFR in patients with periodontitis." (PMID 38491529, 2024). "An online differential expression analysis conducted using OralExplorer revealed several genes that were significantly upregulated in all six periodontitis-related datasets, including IL-1β, SRGN, CXCR1, FGR, ARHGEF2, and PTAFR." (PMID 38491529, 2024).
pneumococcal pneumonia (1 paper, 2020). A febrile disease caused by STREPTOCOCCUS PNEUMONIAE. "In our previous study, Pi Sup itself induced inflammation in lower airway tract with upregulation of platelet activating factor receptor, dominant pneumococcal adhesive and invasive factor, which caused severe pneumococcal pneumonia." (PMID 33117325, 2020).
prostate carcinoma (1 paper, 2022). A carcinoma that arises from epithelial cells of the prostate gland. "PTAFR plays a significant role in mediating the radio-resistance feature of prostate cancer cells." (PMID 35317831, 2022).
streptococcal infection (1 paper, 2014). Any of the several infectious disorders caused by members of streptococcus, a genus of gram positive bacteria belonging to the family Streptococcaceae. "For instance, there is human and mouse data supporting a role for PTAFR gene variants and susceptibility to invasive streptococcal infections." (PMID 24949630, 2014).
Thrombocytopenia (1 paper, 2014). A reduction in the number of circulating thrombocytes. "A recent report describes successful use of two platelet-activating factor receptor antagonists to decrease thrombocytopenia, vascular permeability and mortality in a mouse model of dengue infection." (PMID 24517970, 2014).
viral infection (1 paper, 2023). "In addition, viral infection may compromise the epithelial barrier, alter the mucosal surface environment, degrade antimicrobial peptides, and expose adhesion receptors, such as ICAM-1, CEACAM-1, platelet-activating factor receptor (PAFr), and Fn, thereby facilitating bacterial adhesion and growth." (PMID 37065141, 2023).
tumor (15 papers, 2010 to 2024). "Another previous study revealed PTAFR as a promising target for tumor repopulation induced by radiotherapy in solid tumor." (PMID 35536524, 2022). "While PAF and its receptor PTAFR promote malignant transformation, tumor progression, and chemoresistance, we were able to identify PLA2G7/PAF-AH as counterpart and protective factor." (PMID 34206491, 2021). "It has been reported that activated PTAFR-dependent pathways in tumor cells affect the tumor microenvironment and the phenotype of the tumor-associated macrophages to promote tumor growth." (PMID 33753779, 2021). "PAF is a lipid second messenger secreted into the tumor microenvironment by circulating cells and cancer cells mediating its effect through a specific G-protein-coupled receptor (PTAFR)." (PMID 34206491, 2021). "Later on, it was shown that this apoptosis-induced tumor growth was inhibited if mice were pretreated with antagonists of platelet-activating factor receptor (PAFR)." (PMID 29459885, 2018). "In experimental models, blocking of platelet activating factor receptor reduced tumor growth and increased animal survival." (PMID 30328954, 2018). "These include platelet-activating factor receptor (PAFR) that causes platelet mobilisation and promotes tumour metastases, as well as epidermal growth factor receptor (EGFR) which also promotes tumour invasion." (PMID 27566553, 2016). "PTAFR encodes a seven-transmembrane G-protein-coupled receptor for platelet-activating factor (PAF), which plays a role in oncogenic transformation, tumor growth, angiogenesis, metastasis, and pro-inflammatory processes." (PMID 25343742, 2014). "Consequently, inhibition of PTAFR leads to sensitization to cisplatin chemotherapy and a reduction in tumor growth." (PMID 34206491, 2021). "Pro-tumorigenic effects of platelet activating factor receptor in tumors includes promotion of tumor cell proliferation, production of survival signals, migration of vascular cells and formation of new vessels and stimulation of dendritic cells and macrophages suppressor phenotype." (PMID 30328954, 2018). "The role of PAF and its receptor (platelet-activating factor receptor, PAFR) in tumours has been investigated in recent years." (PMID 30340558, 2018).
cancer (13 papers, 2011 to 2025). A tumor composed of atypical neoplastic, often pleomorphic cells that invade other tissues. "PTAFR is present in various intracellular locations, including the nucleus, and is implicated in a wide range of cancers and disease processes." (PMID 40395233, 2025). "PTAFR is a platelet activating factor receptor associated with many characteristic and inflammatory diseases, but it has been less frequently reported in cancer." (PMID 33765954, 2021). "X-ray exposure under hypoxia compared to that under normoxia also upregulated platelet-activating factor receptor (PTAFR), which has been reported to enhance cancer progression in certain tumors." (PMID 38674080, 2024). "Although It is not the most differentially expressed gene, it is function was studied more thoroughly.PTAFR was known to play a significant part in diverse cancers and diseases." (PMID 36437959, 2022). "PTAFR (platelet activating factor receptor) belongs to the G-protein-coupled receptor (GPCR) family with vital roles in cancer progression via regulating molecular pathways such as STAT3 and PI3K-AKT signaling networks." (PMID 35317831, 2022). "Our previous studies have shown that expression of a G-protein coupled, platelet-activating factor-receptor (PAFR) pathway plays critical roles in pro-oxidative stressors-mediated cancer growth and MVP release." (PMID 33198218, 2020). "As a kind of G-protein coupled receptor, PTAFR has been reported to bind to the platelet-activating factor, then plays a role in a number of biological pathways including inflammatory diseases, cardiovascular homeostasis as well as cancer." (PMID 36437959, 2022). "In the present study, the smoking-related methylation changes to RUNX3, IL6R, PTAFR, and ANKRD11 (cardiovascular-related genes) and CEP135 and CDH23 (cancer-related genes) corresponded to increased gene expression." (PMID 26756918, 2016). "Moreover, PAFAH1B3 loss in vivo sensitized leukemia cells to tyrosine kinase inhibitor (TKI) treatment via the platelet activating factor (PAF)/platelet activating factor receptor (PAFR) signaling pathway, and PAF/PAFR has been found to exhibit beneficial effects in some cancers." (PMID 35534807, 2022).
infection (7 papers, 2013 to 2022). The state of being infected such as from the introduction of a foreign agent such as serum, vaccine, antigenic substance or organism. "Platelet Activating Factor Receptor (PTAFR or PAFR) is exploited by respiratory viruses and bacteria to interact with human cells and initiate infection." (PMID 36589459, 2022). "Inhalation of contaminants increases airway bacterial infection risk; in vitro, exposure to e-cigarette vapor extract increases platelet-activating factor receptor (PAFR) expression and increases pneumococcal adhesion and infection cells." (PMID 33924379, 2021).
inflammation (2 papers, 2022 to 2025). Aberrant reaction of the microcirculation characterized by movement of fluid and leukocytes from the blood into extravascular tissues. "However, in contrast to Oleuropein, Rhoifolin may have cardiotoxicity due to being a possible modulator of the platelet activating factor receptor which is associated with myocardial inflammation." (PMID 35956836, 2022).
bacterial infection (1 paper, 2017). "To test this hypothesis, we measured expression of platelet-activating factor receptor (PAFR), which is associated with increased secondary bacterial infection (32, –, 34) in the lungs of lean and obese mice prior to and 7 days following influenza virus infection." (PMID 28928207, 2017).
epithelial carcinoma (1 paper, 2006). "In addition, VP-16 and the chemotherapeutic agent mitomycin were also found to induce IL-8 and TNF-α production by a human epithelial carcinoma cell line (KB cells) that expressed platelet-activating factor receptor." (PMID 17047652, 2006).
PTAFR also shares sentences with these, for which no sentence is quoted: Alzheimer disease (2 papers); cardiovascular disease (2); idiopathic pulmonary fibrosis (2); acute kidney injury (1); age (1); amyotrophic lateral sclerosis (1); chronic spontaneous urticaria (1); Cognitive impairment (1); coronary artery disease (1); dermatitis (1); fibrosis (1); gestational diabetes mellitus (1); Lung Injury (1); Neurological Disease (1); non-melanoma skin carcinoma (1); Oral Cancer (1); phospholipidosis (1); pneumococcal bacteremia (1); Sepsis (1); Stroke (1); systemic lupus erythematosus (1); Thrombocytosis (1); thrombosis (1); type-2 diabetes (1); upper respiratory infections (1); urticaria (1).